RHOA (ras homolog family member A)
Diseases named in the same sentence as RHOA in open-access papers (continued):
Sharing a sentence is not in itself a finding about the gene and the disease.
lung cancer (continued). "In summary, our work uncovered that Hhex negatively regulated cell migration of lung cancer cells by enhancing RHOGDIA interaction with RHOA/CDC42, which reduced downstream effector CF1 phosphorylation, thus inhibiting cell protrusions formation." (PMID 34321041, 2021). "The Rho kinase pathway has an intimate relationship with cell growth, cell migration, and invasion in lung cancer, it has been found that RhoA knockdown can prevent cell proliferation and induces apoptosis in SPCA1 lung cancer cells." (PMID 32848724, 2020). "It was reported that miR-125a-3p decreased the expression of RhoA to represses cell migration of lung cancer cells." (PMID 32046740, 2020). "To elucidate the molecular mechanism by which BTBD9 regulates TNFAIP1 to affect lung cancer cell migration, we detected the expression level of RhoA, which was reported to be regulated by TNFAIP1 and responsible for stress fiber formation." (PMID 32327643, 2020). "Recent investigations have shown the role of Myo9b-RhoA in mediating the inhibitory effect of SLIT2 on lung cancer cell migration." (PMID 33318575, 2020). "Overexpression of E-cadherin in nonsmall cell lung cancer cells reduces the activity of RhoA and impairs cell migration, concomitantly with the increased membrane association of p190RhoGAP, an inhibitor of Rho GTPases." (PMID 30857262, 2019). "Our data identify a novel Cx43/EGF/ERK1/2/FAK/RhoA/Rac1-dependent signaling axis, which determines the efficiency of lung cancer cell diapedesis." (PMID 30274176, 2018). "Interesting, RALB was required for invasive lung cancer cell behavior through a mechanism dependent on ARHGEF2 activation of the RHOA/ROCK pathway." (PMID 27835861, 2017). "EL decreased phosphorylation of FAK and its downstream targets, Src, paxillin, and decreased mRNA expression of cell motility-related genes, RhoA, Rac1, and Cdc42 in lung cancer cells." (PMID 28068967, 2017). "Fibronectin is known to induce activation of FAK via extracellular signal-regulated kinase (ERK) or PI3K/Akt to increase matrix metalloproteinase (MMP)-9/calpain-2 or MMP-9/RhoA activity, respectively, and lead to lung cancer metastasis." (PMID 26517522, 2016). "Our investigation focuses on addressing the role of RhoA in K-Ras-driven tumorigenesis in vivo in established mouse models of lung cancer." (PMID 26030593, 2015). "Specifically, activated RhoA regulates tumor invasion of lung cancer cells by regulating gene transcription of MMP2 and MMP9." (PMID 25889562, 2015). "The top ranking pathways influenced by HOXA5 include cytoskeleton-related pathways such as IP3 signalling, EMT regulation, cell adhesion, and RhoA regulation, which are of particular interest due to their potential roles in lung cancer invasion and metastasis." (PMID 25875824, 2015). "The extracellular signal-regulated kinase ERK/RHOA/(FAK) network is unregulated in patients with lung cancer." (PMID 26668062, 2015). "Endothelial RhoA is activated by lung cancer cell attachment to brain endothelial cells and TEM, which leads to increased actomyosin contractility and actin cytoskeleton reorganization in human brain microvascular endothelial cells." (PMID 25742314, 2015). "The expression of some known targets of miR-31, such as ITGA5, MMP16, and RHOA, was preliminarily examined in miR-31-transfected cells and lung cancer cells." (PMID 24978700, 2014). "In the Human Protein Atlas, the RhoA is expressed in all normal respiratory tissues while only in 34% of lung cancers, supporting our findings." (PMID 25325012, 2014). "A number of studies in lung cancer cells suggest that RhoA plays important roles in cyclin D1 and cell cycle progression." (PMID 23607551, 2013). "While other proteins such as Rac, Ral and RhoB have previously been suggested to play a role in GGTI effects in other cell lines, our study suggests that the effects of P61A6 on H358 lung cancer cells are largely mediated by RhoA." (PMID 23607551, 2013).
lung cancer (continued). "In our experiment, we showed that the activation of RhoA in response to serum stimulation is blocked by GGTI in lung cancer cells." (PMID 23607551, 2013). "Using immunoprecipitation (IP)-Western, we showed that OSU-HDAC-44 increased the interaction between srGAP1 and RhoA in A549 lung cancer cells." (PMID 20856855, 2010). "In this study, we examined the FAK signalling pathways in relation to calpain-2 and RhoA in fibronectin-mediated lung cancer cell migration and invasion." (PMID 19568240, 2009). "In this study, we propose that fibronectin-induced stimulation of FAK that causes lung cancer cell migration and invasion occurs by the activation of MMP9/calpain-2 and MMP9/RhoA through the ERK and PI3K/Akt signalling pathways, respectively." (PMID 19568240, 2009). "Interestingly, DLC1 downregulation abrogated the negative regulation of ectopic E-cad on RhoA activity, thereby allowing anchorage-independent growth and migration in lung cancer." (PMID 40354489, 2025). "Additionally, as a downstream effector of RhoA GTPase, ANLN activates RhoA-mediated signaling to enhance actomyosin contractility, a mechanism recognized as essential for promoting lung cancer cell migration and invasion." (PMID 41573677, 2025). "RHOA is activated upon binding of chemokines, cytokines, and growth factors and its product is one of the major inducers of lung inflammation and acute lung injury, as it inhibits apoptosis and promotes the proliferation of lung cancer cells." (PMID 40722786, 2025). "Hence, C. sinensis likely exerted a protective effect against NSCLC by suppressing the RhoA gene, then recruiting immune cells, enhancing immune function, and inhibiting lung cancer via the MAPK pathway." (PMID 38528546, 2024). "RHOA/CDC42‐CFL1 axis is critical in mediating the tumour cell migration in lung cancer." (PMID 36822595, 2023). "SLIT2 suppresses the migration and invasion of lung cancer cells by regulating RhoA activity." (PMID 35053460, 2022). "Therefore, western blot and real-time PCR analyses were used to detect the expression of RhoA, RhoB, and RhoC in A549, H446 lung cancer cells transfected with plasmid Prox1 and interfering siRNA." (PMID 34183992, 2021). "It has been reported that RAC1 or RhoA are mutated in cancers, and the expression levels of RAC1 or RhoA are aslo altered, which means that RhoA may play an crucial role in lung cancer treatment." (PMID 32848724, 2020). "A recent study highlighted that RhoA might be important for the proliferation and apoptosis in lung cancer cells." (PMID 31791311, 2019). "Furthermore, the activity of RhoA, which promoted the metastasis of lung cancer, increased with the knockdown of DPYSL3." (PMID 29514686, 2018). "It is possible that in lung cancer, Rock 1 may be the major regulator of the RhoA-Rock-pMLC-2 signaling pathway in focal adhesion formation." (PMID 29899821, 2018). "Although the inverse activity relationship between Rac and RhoA remains to be established, both Rac1 and RhoA activation seems to exist in Crk overexpressing lung cancer cells through Dock families or other molecules such as Src, Fak, and Abl those can be activated by Crk." (PMID 27027347, 2016). "Our data suggest that the inhibitory effects of GAP on RhoA could partially explain the suppression of migration and invasion in lung cancer cells." (PMID 25875824, 2015). "In order to assess whether RhoA is required for K-Ras-induced lung cancer initiation, we utilized the K-RasG12D Lox-Stop-Lox murine lung cancer model in combination with a conditional RhoAflox/flox and RhoC-/- knockout mouse models." (PMID 26030593, 2015).
lung cancer (continued). "Recent studies in pancreatic cancer and lung cancer cells showed that ectopically expressed Vav1 acts as an upstream activator of Rac1, RhoA and possibly Cdc42 signaling pathways in response to extracellular stimulation, leading to cytoskeleton changes in cancer cells." (PMID 23342133, 2013). "Our data suggest that fibronectin-mediated activation of FAK that leads to lung cancer metastasis could occur through ERK or PI3K/Akt regulation of MMP9/calpain-2 or MMP9/RhoA activity, respectively." (PMID 19568240, 2009). "Hence, the proposed G-Rh1 compound should be subjected to further experimental validation and may be used as a lead molecule for ROCK1 and RhoA inhibition and apoptosis regulation in treating and managing lung cancer." (PMID 36500403, 2022). "Therefore, RhoA/ROCK1 could be an ideal candidate target in lung cancer treatment as it is found to be highly expressed in cancer." (PMID 36500403, 2022). "In addition, RhoA activation has recently been shown to promote lung cancer EMT and metastasis." (PMID 33227088, 2020). "In addition, HTPB markedly decreased RhoA activity in lung cancer cells." (PMID 22279574, 2012). "Examples include BAP1 in cervical and lung cancer, CDK1 in bladder cancer, E2F2 in ovarian cancer, and RHOA, VEGF, NUMB, among others, in oral cancer." (PMID 41373532, 2025). "Rho‐associated protein kinase 1 (ROCK1) is a key serine/threonine kinase downstream of Ras homolog gene family, member A (RhoA), and the activation of RhoA/ROCK1 signaling can promote the invasion and migration in various cancer types, including lung cancer." (PMID 39023191, 2024). "RhoA/ROCK1 signaling promotes cell migration, invasion, and metastasis in many cancer types, including lung cancer." (PMID 39023191, 2024). "Luteolin repressed cell metastasis in lung cancer via Src/FAK and its downstream Rac1, Cdc42, and RhoA pathways." (PMID 36874921, 2023). "It has also been reported that deletion of p120 can inactivate RhoA but increase the activity of CDC42 and Rac1 and promote the proliferation and invasion of lung cancer cells." (PMID 35251170, 2022). "In lung cancer, overexpression of ALOX12 facilitated cell growth and migration by promoting RhoA and NF-κB activity." (PMID 34291083, 2021). "Similar reductions of RhoA-GTP by Tazemetostat and the kinase inhibitors were observed in three other lung cancer lines (NCI-H23, NCI-H460, and SW900) that express DLC1 mRNA but lack detectable DLC1 protein." (PMID 34862367, 2021). "To investigate the effect of RHPN2 on the RhoA activity, we performed RhoA pull-down activation assay in RHPN2-expressing lung cancer cells." (PMID 33552953, 2020). "The RhoA pull down assay and Western blotting were performed to elucidate the mechanism of RNPN2 in tumorigenesis of lung cancer." (PMID 33552953, 2020). "In addition to its roles in enhancing cell proliferation, migration, and EMT, and activating pathways such as PI3K/AKT and RhoA, ANLN has also been found to promote lung cancer progression by inhibiting pyroptosis." (PMID 41573677, 2025). "Interestingly, MYO9B was shown to physically interact with the intracellular domain of Robo1 in lung cancer cells, leading to MYO9B inhibition and RhoA activation upon Slit addition." (PMID 37675403, 2023). "Another previous study exploring the interaction partners of ARHGEF39 identified RAC1, but not RHOA (or CDC42) in a pulldown assay from lung cancer cells overexpressing ARHGEF39." (PMID 35959104, 2022). "A recent study has added that ARHGEF39 is necessary for RAC1 activation during migration of lung cancer cells in response to growth factors, but this study did not investigate any potential activation of RHOA." (PMID 35959104, 2022). "Moreover, PG has inhibited RhoA and MMP-2 protein expression in lung cancer 95-D cell line resulting in invasion inhibition." (PMID 28714874, 2017).
lung cancer (continued). "Subsequently, RhoA has been found to be either overexpressed or hyperactive in a variety of cancers, and RhoA activity is correlated with negative outcomes in gastric, hepatocellular, esophageal squamous cell, breast and lung carcinomas." (PMID 26030593, 2015). "Suppression of CNTN1 expression abolished the ability of lung cancer cells to invade and metastasize by activating RhoA, but not Cdc42 or Rac1, suggesting that CNTN1 is a key regulator of invasion and metastasis in lung adenocarcinoma." (PMID 22580838, 2012). "Moreover, G-Rh1 reduced the RhoA and ROCK1 gene expression in the A549 lung cancer cells." (PMID 36500403, 2022). "Generally, these data indicated Hhex could inhibit RHOA and CDC42 activation in lung cancer cells." (PMID 34321041, 2021). "Thus, we tested whether RHPN2 could affect RhoA activity and subsequently regulate Hippo-YAP pathway in lung cancer cells." (PMID 33552953, 2020). "Although there are numerous suggestions that the ECM promotes cancer cell migration and invasion through FAK signalling, the mechanism by which ECM fibronectin regulates FAK activity in lung cancer cells, particularly in relation to calpain-2 and RhoA, has not yet been explored in detail." (PMID 19568240, 2009). "MiR-614 was found to inhibit cell proliferation, CHD4 regulates both proliferative and migratory abilities of NSCLC cells via the RhoA/ROCK pathway, while the role of DPY30 has not yet been clarified in lung cancer." (PMID 40282457, 2025). "Though regulation of PTEN activity by the RhoA/ROCK signaling pathway does not seem to contribute to the in vitro survival of normal prostate stem cells, it has been shown to play an essential role in Ras-induced tumorigenesis of lung cancer cells." (PMID 21464902, 2011).
colorectal cancer (90 papers, 2009 to 2026). A primary or metastatic malignant neoplasm that affects the colon or rectum. "Our findings revealed that RhoA expression is significantly associated with the clinical stage of colorectal cancer." (PMID 39887960, 2025). "It was also shown earlier that loss of Tpm2.1 in colorectal cancer cell line HS675T upregulated the levels of active RhoA." (PMID 36278174, 2022). "The Ras homolog gene family, member A (RhoA), is associated with invasion and poor prognosis in colorectal cancer." (PMID 33953222, 2021). "RHOA is widespreadly overexpressed in prostate cancer, cervical cancer and colorectal cancer, and associated with cancer metastasis." (PMID 31820783, 2020). "Tight junction-associated protein GEF-H1/RhoA coordinates the remodeling of the cytoskeleton and is engaged in cancer metastasis including colorectal cancer." (PMID 32724467, 2020). "LARG binds to LRRFIP1/GCF2 and mediates the integrin signaling pathway, causing RhoA activation, leading to the stimulation of cytoskeletal remodeling, increased migration, and invasion of metastatic colorectal cancer cells." (PMID 30709060, 2019). "Moreover, loss-of-function mutations in RhoA have been revealed in various cancers, and RhoA inactivation can promote colorectal cancer growth and skin tumor formation." (PMID 32789168, 2020). "On the basis of in vitro results, the present study was aimed to determine whether the recombinant adenovirus mediated 4-tandem linked shRNA construct targeting RhoA and RhoC genes may inhibit the growth of human colorectal cancer cell graft implanted in nude mice in vivo." (PMID 20828398, 2010). "Our previous studies have also demonstrated that the over-expression of RhoA and RhoC occured in colorectal cancer tissues from Chinese patients and RhoA and RhoC shRNAs in tandem linked expression could markedly inhibit the invasion and migration potentials of colorectal cancer cells." (PMID 20828398, 2010). "We then detail procedures for investigating the effects of the compounds on RhoA signaling in cancer cells and mouse colorectal cancer (CRC) models." (PMID 41984592, 2026). "HIF1α-mediated RHOA upregulation has been suggested across multiple types of cancers, including hepatocellular, lung, breast and colorectal cancer." (PMID 40600795, 2025). "Through literature research, we found that MYO1B is associated with the development of various malignancies and enhances tumor cell migration and invasion in colorectal cancer by activating the RhoA/ROCK/FAK signaling pathway." (PMID 41278212, 2025). "IRX5 promotes metastasis via RHOA signaling in colorectal cancer and regulates WNT/β-catenin pathways, which intersect with FAT1-mediated Hippo signaling." (PMID 40672387, 2025). "In conclusion, our study demonstrates that mechanical stimulation significantly enhances the expression of RhoA and Rac1 in colorectal cancer cells, with a clear correlation between biomarker levels and cancer stage." (PMID 39887960, 2025). "In colorectal cancer, it enhances tumor cell migration and invasion by activating the RhoA/ROCK/FAK signaling pathway, thereby promoting metastasis." (PMID 41278212, 2025). "Analysing RhoA and Rac1 protein levels in Colorectal cancer (CRC) samples under mechanical strain highlights their potential as diagnostic markers." (PMID 39887960, 2025). "Our investigation focused on the expression of RhoA in clinical cells collected from human colorectal carcinoma specimens and the cells purchased from ATCC." (PMID 39887960, 2025). "A previous study has also shown that mTORC1 and mTORC2 promote EMT-mediated metastasis through activation of RhoA and Rac1 in colorectal cancer." (PMID 38792011, 2024). "YTHDF1 is significantly associated with metastatic gene signatures through ARHGEF2 translation and RhoA signaling activation in colorectal cancer." (PMID 39185313, 2024). "As with colorectal cancer, chemical RhoA inhibitor attenuated STAT3 activation in hepatoma cell line." (PMID 37752569, 2023).